IL6 (interleukin 6)
Diseases named in the same sentence as IL6 in open-access papers (continued):
Sharing a sentence is not in itself a finding about the gene and the disease.
diabetes (continued). "Clinical studies found that proinflammatory factors such as interleukin-6 (IL-6) and C-reactive protein (CRP) were significantly higher for the population who developed diagnosed diabetes over the follow-up period, and to some degree, these indicators could be used as powerful predictors of T2D." (PMID 33224253, 2020). "Thus, although other interleukins such as IL-6 were found to be related to diabetes, Il-29 seems not to take part in microvessel damage in the course of diabetes." (PMID 31936869, 2020). "IL-6 was significantly predicted by nonwhite race (B = 0.17, p < .05), being retired (B = 0.27, p < .01), history of diabetes (B = 0.26, p < .01), alcohol consumption (B = −0.05, p < .01), antihypertensive use (B = 0.18, p < .01), and exercise (B = −0.20, p < .01)." (PMID 32793814, 2020). "Furthermore, the serum levels of some inflammation‐related biomarker are much higher compared to those without diabetes, such as IL‐6, serum ferritin, ESR and CRP." (PMID 32233013, 2020). "The results showed that protein secretion of IL-1β, IL-6 and MCP1 in the STZ/STZ-CTL group increased to 197%, 184%, and 151%, respectively, compared to the CTL/CTL-HSC group, and STZ/CTL-HSC group completely reversed, while the CTL/STZ-HSC group mimicked, the maternal diabetes-induced effect." (PMID 33101089, 2020). "Interestingly, this trend was maintained for IL-6 even when we limited the analysis to people with no diabetes." (PMID 34104801, 2020). "Besides, CW could significantly decrease the elevation of IL-6 and ICAM-1 levels induced by diabetes mellitus in the rat retina (P < 0.05 and 0.05 compared with the DM group)." (PMID 32082400, 2020). "Increased proinflammatory cytokines such as interleukin-1β (IL-1β) and interleukin-6 (IL-6), promote BRB breakdown and increase microvascular impairment, which contribute to the increase of vascular permeability by different signaling pathways in diabetes-induced retinal pathology 12-14." (PMID 32210708, 2020). "As a main proinflammatory mediator, IL-6 has a direct toxic effect on islet cells and can upregulate the expression level of ICAM-1, mediated by IL-1-induced by reactive oxygen species, leading to further damage to the epithelium, as well as accelerating the onset of diabetes." (PMID 32082400, 2020). "In fact, elevated levels of inflammatory markers [interleukin-1β (IL-1β), tumour necrosis factor-α (TNF-α), interleukin-6 (IL-6), interleukin-8 (IL-8), and C-reactive protein (CRP)] were shown to increase neutrophil apoptosis and impair neutrophil clearance in patients with diabetes." (PMID 31827375, 2019). "In this study, heat-killed S. thermophilus may also affect diabetes through the BMID axis by increasing the abundance of beneficial bacteria, protecting the intestinal epithelial barrier, and suppressing IL-6, LPS, and TNF-α secretion, and the end result is moderation of insulin tolerance." (PMID 31223540, 2019). "Diabetes in this case becomes a confounding factor, in that it establishes a low-grade inflammatory state, characterized by elevated levels of acute phase reactants such as CRP, interleukin-6 (IL-6), secretory phospholipase A2 and tumor necrosis factor alpha (TNFα)." (PMID 29547660, 2018). "However, after adjustment for age, sex, diabetes mellitus, BSA, PD vintage, history glucose exposure, nPCR and RRF, serum IL-6 [β = 0.048 (0.019–0.077), P = 0.001] and serum Ang-1 [β = − 0.068 (− 0.127,-0.010), P = 0.003] were independently associated with Prcl." (PMID 29792163, 2018). "The findings for IL-6 emphasise that results may differ between individuals without and with diabetes, so that diabetes status should be investigated as potential effect modifier in future studies." (PMID 29520075, 2018). "HF animals presented neither diabetes nor hypertension and only a mild elevation in the proinflammatory cytokines IL-6 and TNF-α in serum, that, in spite of non-significant may be indicative of ongoing systemic inflammation process." (PMID 28358868, 2017).
diabetes (continued). "Some of our data suggest that the contribution of non-canonical WNT5A signaling to IL-6 production and inflammation may be particularly relevant in subjects with diabetes, which typically exhibit high levels of systemic inflammation." (PMID 29229927, 2017). "However, in the context of diabetes, the expression of REG3A was impaired in skin wounds and SHP-1 was observed to be diminished in parallel, thus leading to excessive production of TNF-α and IL-6 and delayed wound healing." (PMID 27830702, 2016). "In Müller cells, FT011 reduced diabetes-induced gliosis and vascular endothelial growth factor (VEGF) immunolabeling and the hyperglycaemic-induced increase in ICAM-1, monocyte chemoattractant protein-1, CCL20, cytokine-induced neutrophil chemoattractant-1, VEGF and IL-6." (PMID 26222724, 2015). "Furthermore, the spontaneous production of IL-6 by CD33-/lowplasmacytoid dendritic cells from patients with diabetes without atherosclerotic complications has been reported." (PMID 22500980, 2012). "With the onset of diabetes, adipokines such as TNF-α and IL-6 may contribute to insulin resistance." (PMID 23267348, 2012). "In fact, diabetes is considered an inflammatory disease that is characterized by increases in oxidative stress (e.g., the oxidation of glucose) and advanced glycation end-products (AGE), which induce the up-regulation of many inflammatory cytokines, such as MCP-1, TNF-α, IL-1, and IL-6." (PMID 21984919, 2011). "However, in patients undergoing renal replacement therapy (either hemodialysis or continuous peritoneal dialysis), irrespective of the presence of diabetes mellitus, the serum levels of inflammatory markers (i.e., IL-6, IL beta, IL 10, or TNF alpha) are heterogenous." (PMID 38921685, 2024). "Notably, the pro-inflammatory markers C-reactive protein (CRP), interleukin-1β (IL-1β), interleukin-6 (IL-6), NF-kB, and tumor necrosis factor-alpha (TNF-α) contribute to the chronic inflammatory state of T2DM and are significantly elevated in patients with diabetes." (PMID 39062550, 2024). "Additionally, ex vivo culture conditions, including glucose levels, may not fully replicate the hyperglycemic state typical of diabetes, potentially influencing IL-6 output." (PMID 39456722, 2024). "Consequently, a refined selection comprising seven genes (MMP2, MMP9, IL17A, IL10, FGF2, IL6 and VEGFA) and eleven pharmacological agents has emerged, exhibiting promise in delivering therapeutic effects aimed at mitigating the occurrence of OP in individuals afflicted with diabetes." (PMID 38250601, 2024). "In the present study, we found that SDE alleviates IL-6, IL-8, and MCP-1 levels, and we also found that SDE alleviates TNF-α expression, which was commonly observed in DR tissues These results indicate that SDE may be a potential therapeutic agent for diabetes mellitus treatment." (PMID 37139437, 2023). "However, diabetes did not significantly alter the release of IL-6 and IL-10 in CABG patients." (PMID 35935655, 2022). "In patients with diabetes, impaired insulin signalling might lead to chronic subclinical low-grade inflammation via activation of AP-1 and NF-κB leading to a decrease in anti-inflammatory cytokines and to an increase in the pro-inflammatory cytokines TNF-α, IL-6 and IL-1β." (PMID 35253006, 2022). "Therefore, the significantly reduced cytokines (IL-1α, IL-6 and TNFα) levels in the hippocampus of the DB and DAV groups, contrary to previous reported increases, may suggest a compromised immune response and prolonged diabetes." (PMID 35453953, 2022). "However, the relationship between HuR and IL-6 in diabetes has not been evaluated." (PMID 35597446, 2022). "COMF and its active components quercetin, kaempferol, isorhamnetin, luteolin and apigenin could regulate AKT1, VEGFA and IL-6 mRNA levels and improve the dysregulation of PI3K-AKT pathway signaling to intervene the inflammation and trauma manifested during the development of diabetes." (PMID 36559019, 2022).
diabetes (continued). "In the present study, we observed that the synbiotic combination decreased the key cytokine IL-6 among other proinflammatory markers (IL-8, IL17a and IFNγ) after only 30 days of treatment in healthy middle-aged volunteers without any suspicion of type 2 diabetes mellitus and cardiovascular diseases." (PMID 33514774, 2021). "In addition, it has been reported that serum level of inflammatory cytokines, including IL-6, in COVID-19 patients with diabetes is higher than those patients without diabetes resulting in increased susceptibility to COVID-19-related infections in diabetic patients." (PMID 34307358, 2021). "Moreover, GapmeR-mediated knockdown of human DNM3OS in human THP1 monocytes inhibited inflammatory genes (IL6, TNF, and ITGAX) and phagocytosis similar to actions of the mouse ortholog, suggesting DNM3OS upregulation in humans likely contributes to enhanced inflammation in diabetes." (PMID 34234740, 2021). "As supported by a cross-sectional survey on 1914 elder individuals aged 70–79 years without overt diabetes and cardiovascular events, there was a positively graded relationship between number of MetS diagnostic components and increased circulating levels of CRP and IL-6." (PMID 29670915, 2018). "People with DM and periodontitis usually have elevated circulating proinflammatory mediators, like TNF-α, IL-6, CRP, and reactive oxygen species (ROS) that can interfere with diabetes metabolic control and may act synergistically in worsening cardiovascular complications in diabetes." (PMID 30356347, 2018). "Our results indicate that diabetes acts through other mechanisms to promote atherosclerosis, and further suggest that macrophage production of IL-6 or TNF-α might not explain diabetes-accelerated atherogenesis since these cytokines were significantly altered by EP4-deficiency." (PMID 27351842, 2016). "However, at an advanced-stage of the disease, at the critical stage of ischemia of the lower extremities, the concentration of IL-6 was nearly twice as high, and E-selectin levels showed an upward trend in patients with diabetes compared topatients without diabetes." (PMID 27834825, 2016). "Although diabetes is clearly associated with impaired EDC-mediated repair of myocardium and greater LTS score, poorer glycemic control (i.e., greater HbA1c) alone did not linearly correlate with changes in IL-6 (p = 0.69), SDF1α (p = 0.43) and exosome production (p = 0.82)." (PMID 27225482, 2016). "HIF-1α levels positively correlated with CRP (r = 0.226, P = 0.023), IL-6 (r = 0.316, P<0.001), UKPDS risk score (r = 0.144, P = 0.009), HbA1c (r = 0.242, P<0.001) FBG (r = 0.244, P = 0.029), and CAC scores (r = 0.360, P<0.001), but did not correlate with diabetes duration, age, and LDL." (PMID 24564828, 2014). "Also, there are some evidences that IL-6 indirectly induces VEGF in vitro and our results that vitreous level of VEGF was well correlated with duration of diabetes and grade of retinopathy in control eyes support the hypothesis that PRP-induced expression of VEGF was much slower than that of IL-6." (PMID 23675018, 2007). "Although there were correlations between cognitive performance and various cognitive scores, IL‐6, MDA, NSE, VCAM‐1, and TNF‐α did not play a mediator role in the neuropathology of diabetes‐related cognitive impairment." (PMID 39829127, 2025). "The results of the moderator analysis indicated that NSE, IL‐6, MDA, and TNF‐α did not exhibit a moderating effect on diabetes‐related cognitive impairment." (PMID 39829127, 2025). "In the moderator analysis, no moderating effect of the biomarkers NSE, IL‐6, and MDA on the impact of diabetes on cognitive scores was observed (p > 0.05)." (PMID 39829127, 2025). "Similar to our findings, a study on LLD in patients with diabetes found elevated markers like CRP and IL-6 but no prediction of dementia over a 10.6-year follow-up." (PMID 39922907, 2025).
diabetes (continued). "The non-response cohort was older, more likely to have diabetes, and had higher levels of D-D polymers, Pro-BNP, direct bilirubin, and inflammatory markers, including ferritin, C-reactive, procalcitonin, IL-6, IL-10, and IL-17A than the response cohort." (PMID 41426569, 2025). "There is reduction in pro-inflammatory markers like hsCRP, IL-6, IL-1β, TNF-α, and IFN-γ in patients with diabetes and in vitro models without diabetes, while there is a change in polarity from M1 to M2 macrophages when treated with SGLT2i." (PMID 40868177, 2025). "NDUFS1 exhibits a negative correlation with IL6 and TNF, suggesting a potential link to inflammatory processes in the context of diabetes or sarcopenia." (PMID 40869253, 2025). "The year of publication, clinical biochemical parameters, carotid intima-media thickness, IL-6, CTRP9, smoking, hypertension, and diabetes categorization were not sources of heterogeneity." (PMID 40600192, 2025). "Regarding the group with diabetes, at baseline (T0), it was evidenced positive significant correlations both between circulating levels of TNF-α and IL-6, and between levels of IL-10 and EMP, as well as a negative significant correlation between IL-10 and PMP." (PMID 39253540, 2024). "As expected, this study demonstrates significantly increased IL-6, IL-8, IL-18, and MCP-1 expression in patients with diabetes, with and without VCs, compared to the control group." (PMID 39519313, 2024). "The likelihood of delirium was estimated by calculating the total score for the presence or absence of diabetes, CRP values, and IL-6 severity at admission." (PMID 38523173, 2024). "The total amounts of MIP-1α, IL-2, IL-6, IL-17, and TGF-β were significantly increased in the non-diseased sites of diabetes patients (p < 0.05), compared to those in the control group." (PMID 37835794, 2023). "In contrast, another research found that circulating IL‐6 and hs‐CRP are not improved in subjects affected with diabetes after consuming 500 mg/day of hesperidin for 2 months." (PMID 38107097, 2023). "Comparatively, on the other hand, NDD-CKD patients with anemia had lower eGFR but were older, had more diabetes, and had higher sFas/ eGFR, EPO/Hb ratios, and serum levels of IL-6 and sFas than NDD-CKD without anemia for an extended period." (PMID 37390095, 2023). "In another study conducted by Wang and colleagues comprising patients with diabetes mellitus, LDH, PCT, CRP, ferritin, and IL-6 were significantly increased in ICU patients compared to non-ICU patients." (PMID 35746755, 2022). "People with diabetes infected with SARS-CoV-2 have been observed to have much higher levels of interleukin-6 (IL-6) and C-reactive protein (CRP) than individuals without diabetes." (PMID 34578858, 2021). "According to a recent meta-analysis, saffron is effective in improving the levels of inflammatory markers such as TNF-α, IL-6 and CRP when administered at specific doses (≤30 mg/day) in young adults (<50 years old) lacking a diabetes diagnosis." (PMID 34959826, 2021). "One clinical trial indicated that eight weeks of probiotic yogurt treatment significantly reduced the TNFα level, but while levels of IL-6 and CRP were also decreased, these findings were not statistically significant among those with diabetes." (PMID 33557067, 2021). "In contrast, cells infected with diabetes-related EV strains secreted enhanced levels of IL8, IL18, and MCP1, but not of IL6." (PMID 32664675, 2020). "In our study, patients of acromegaly with diabetes had higher CAL and PD, though non-significant, from acromegaly without diabetes and had significantly higher levels of IL-6." (PMID 33154456, 2020). "In our study, there was an upregulation of IL-6 and TNF-α in CRC animals with or without diabetes induction in the CRC and DCRC groups." (PMID 32664279, 2020). "Long‐term diabetes significantly increased plasma levels of TNF‐α, IL‐1 β and IL‐6 in diabetic rats without daily oral kirenol administration." (PMID 31565849, 2019).
diabetes (continued). "At 24 h, 48 h and 72 h post-infection, the levels of IL-1Ra, IL-6, IL-8, IL-10, IL-12p40, TNF-α, MCP-1, and MIP-1b were still low in ESRD without diabetes group than in the control group." (PMID 31875015, 2019). "IL6 transcript levels in VAT also correlated with the expression of the intracellular PCP signaling modulators DHS1,2,3 in subjects with diabetes, but not in those without diabetes." (PMID 29229927, 2017). "Serum markers of pro-inflammatory cytokines IL-6 and MCP-1 were not significantly different between the study groups, but elevated serum concentrations of MCP-1 were noted in rats with diabetes." (PMID 29095895, 2017). "IL6 -174G > C was in HWE in both cases and controls whereas IL6 -572G > C only reached HWE among the diabetes cases (P = 0.636) and not among those without diabetes (P = 0.006)." (PMID 26911440, 2016). "We examined nitric oxide (NO), IL-6, and TNF-α secretion from cultured palmitate-stimulated PBMNCs or in the plasma from type 2 diabetes mellitus (T2MD) patients or nondiabetic (ND) controls." (PMID 24803982, 2014). "At variance with IL-1β, the retinal expression of IL-6 and TNF-α was not changed in diabetes at any of the time points tested." (PMID 22615852, 2012). "Lack of TNFα increased higher basal VCAM-1 protein and sVCAM-1, but failed to up-regulate IL-6 and IL-1β mRNA and VCAM-1 protein in response to diabetes." (PMID 20856927, 2010). "Although there were correlations between cognitive performance and various cognitive scores, mediator analysis results indicated that the biomarkers IL‐6, MDA, NSE, VCAM‐1, and TNF‐α did not play a mediating role in the neuropathology of diabetes‐related cognitive impairment." (PMID 39829127, 2025). "Diabetes increased IL-10, IL-17, IL-22, and TNF-α levels, and reduced IL-1β levels in the colon of diabetic mice compared to non-diabetic controls, without altering the content of IL-4, IL-6, and TGF- β1." (PMID 40496562, 2025). "A higher IL-6/IL-10 ratio was found in patients with diabetes compared to the group without diabetes at T0 and T1, whereas an increased IFN-γ/IL-10 ratio was only found at T1 in patients with diabetes in comparison to the group without diabetes." (PMID 39253540, 2024). "In this study, we aim to shed more light on the role of IL6 in insulin secretion and glucose metabolism by exploring the expression patterns of IL6 and IL6R in human pancreatic islets from donors with/without diabetes and their correlation with HbA1c, BMI, age, and gender." (PMID 38667300, 2024). "Besides, at T0, it was evidenced positive correlations both between circulating TNF-α and IL-6, and IL-10 and EMP, as well as a negative correlation between IL-10 and PMP in the group with diabetes." (PMID 39253540, 2024). "Higher circulating NET levels were a significant predictor of increased risk of initial ICU admission, in-hospital mortality (adjusted HR 3.21, 95% CI 1.08–9.19) and AKI (OR 3.67, 95% CI 1.30-10.41), independent of age, diabetes, pre-existing CKD and IL-6 levels." (PMID 37051234, 2023). "Diabetes mellitus as well as increased levels of CRP and ferritin were found to be the strongest predictors for a poor outcome, and this was not the case for increased levels of IL-6 as was mentioned before." (PMID 38034537, 2023). "In our previous work, it was suggested that IL-6 has a positive effect on hepatocytes in the liver with NAFLD by blocking trans-signaling IL-6 and activating non-canonical signaling pathway NF-kB in patients with type 2 diabetes mellitus." (PMID 36830933, 2023). "Besides sFRP5, parameters of glucose status: glucose and HOMA-IR, inflammatory markers: IL-6 and CRP showed significant differences between healthy controls and diabetes subjects, but not between subjects with and without DPP4i treatment." (PMID 36056109, 2022).